VIM (vimentin)
Diseases named in the same sentence as VIM in open-access papers (continued):
Sharing a sentence is not in itself a finding about the gene and the disease.
tumor (continued). "CAFs and tumor cells need reciprocal communication to stimulate mediators such as vimentin, matrix metalloproteinase (MMPs); periostin; Insulin growth factor-2 (IGF2); IL-33; and CXCL12, related to and tumor growth, invasion, and downregulation of tumor suppressor genes." (PMID 34204259, 2021). "This interface area was also investigated using immunofluorescence by increased magnification, and several cells with combined reaction of KLF4, cytokeratin and vimentin were detected, which might be considered as EMT tumor cells." (PMID 33802627, 2021). "In addition, MACC1, E-cadherin and vimentin levels were correlated with cancer staging and TNM tumor classification." (PMID 33854976, 2021). "The cells expressing Vimentin, S100A4, and αSMA are likely to be resting or activated fibroblasts that may play an important role in this type of neoplasia." (PMID 33761962, 2021). "Furthermore, the results of Western blotting of the tumor showed that PCNA, cyclin D, and vimentin protein were substantially overexpressed in the scramble control group in comparison with the MICAL2-knockdown group." (PMID 34868922, 2021). "Similarly, mRNA levels of vimentin, N‐cadherin, E‐cadherin, CK‐19, MMP‐9, and MMP‐2 in tumour tissues were consistent with the gene expression results in Linc00485‐silenced A549 cells." (PMID 33237626, 2021). "Besides tumor cells with a basal phenotype characterized by SMA expression, Vimentin, and EMT-like tumor cells, TNBC clinical specimens also consist of fibroblasts, endothelial and immune cells." (PMID 34063254, 2021). "In addition, metastasis to lung and liver were detected in tumor-bearing animals as shown by IVIS and vimentin staining." (PMID 34438836, 2021). "Thus, PLK1-induced phosphorylation of vimentin is a coordinator of metastatic tumorigenesis in LUAD through activation of TGF-β signaling for metastasis and expression of PD-L1 by p-Smad2/3 for tumor survival." (PMID 33963314, 2021). "Though VIM expression’s prognostic significance was not assessed in this study, authors alluded to the possibility of circ-VIM as a tumor promoter." (PMID 34794438, 2021). "Epithelial–mesenchymal transformation (EMT) is a pivotal feature of tumor metastasis and may be regulated by EVs’ intercellular transport, so we analyzed the expression of EMT-related markers E-cadherin, N-cadherin, and Vimentin at mRNA levels." (PMID 34884671, 2021). "In Slug-positive tumors, 4.0 ± 2.6% of tumor cells were cytokeratin/vimentin double positive compared with 1.9 ± 1.8% in Slug-negative tumors (p = 0.001)." (PMID 33673269, 2021). "Treatment with either APX2009 or Devimistat which should lead to a decrease in cancer cell metabolism did indeed translate to a significant decrease in tumor volume as well as tumor weight and did not obliterate the CAFs as indicated by vimentin positivity." (PMID 34376225, 2021). "Weakening of this interaction increased the stability of Snail; in turn, translocation of the stable Snail protein into the nucleus was promoted, subsequently reducing E-cadherin level but increasing vimentin and N-cadherin levels, and finally inducing EMT and promoting tumor metastases." (PMID 34345201, 2021). "Increased levels of CD44, vimentin, and OCT3/4, along with a decreased expression of E-cadherin were found in tumor spheres compared to parental cells, indicating the occurrence of an epithelial mesenchymal transition (EMT) and/or the acquisition of a stem-like phenotype." (PMID 33922104, 2021). "Additionally, the brains of tumor-bearing animals were stained with human-specific Vimentin (Clone: SP20, 1:600, NeoMarkers) to identify tumor cells." (PMID 33727611, 2021). "Additionally, easily recognized participations in tumor metastasis, epithelial-mesenchymal transition (EMT) related proteins including N-cadherin, E-cadherin, Vimentin and Snail were detected in RKO and HCT116 cells." (PMID 33726765, 2021).
tumor (continued). "In gastric NENs tumor tissues, the epithelial markers Claudin-1, Zo-1 and E-cadherin were down-regulated, while the mesenchymal markers Vimentin and β-catenin were up-regulated as compared to non-tumorous tissues (p < 0.05)." (PMID 34037532, 2021). "YAP, IGF-1R, and EMT markers (VIMENTIN, SNAIL1, and N-CAD) were visibly expressed in tumor tissues." (PMID 34359714, 2021). "Vimentin expression increased in accordance with tumor progression of CRC, and the tumors with high expression of vimentin had a greater extent of tumor invasion to the serosa, lymph node metastasis and liver metastasis than those with low expression of vimentin." (PMID 34214117, 2021). "The EM033 cells, derived from a stage IA tumor with dedifferentiated endometrioid histology, displayed a high EMT status, characterized by absence of E-cadherin (CDH1) and cytokeratin (KRT) and the presence of vimentin (VIM) on both protein and mRNA level." (PMID 34936030, 2021). "Immunohistochemical analysis revealed that the tumor cells were positive for vimentin and negative for α-smooth muscle actin, CD34, desmin, and β-catenin." (PMID 33829348, 2021). "The tumor cell immunophenotype was positive for vimentin, EMA and negative for CK-pan, TTF-1, CAM5.2, S-100, calponin, SMA, desmin, ALK, CD31 and CD34." (PMID 32039736, 2020). "Since EMT is crucial, although not indispensable, for initiating the process of tumor metastasis cascade, Vimentin has gained much attention as an essential marker for EMT8,36,37." (PMID 33046716, 2020). "Vimentin was profuse in tumor tissue and at the tumor border, whereas GFAP staining was only profuse at the tumor border and more heterogeneously expressed throughout the tumor." (PMID 32977526, 2020). "By well-controlled, routine immunohistochemical stains, the tumor cells were immunoreactive for vimentin, while they were negative for actin, desmin, S-100 and CD34 antibodies." (PMID 32605652, 2020). "In our LATS1/2 cKO mouse model, although some of the tumour markers were highly present in the centre of the tumour mass, e.g., ANKRD1, Vimentin, CK18, nestin and Ki67, some were localised towards the edges of the tumour, e.g., HOPX, AMOTL2, AXL and microglial marker C3." (PMID 32404936, 2020). "Immunohistochemically, the tumor cells expressed cytokeratins and vimentin and were negative for lymphoid markers." (PMID 32979929, 2020). "The immunohistochemical findings demonstrated that the tumor cells were positive for vimentin, CD34, and actin but negative for chromogranin A." (PMID 32441904, 2020). "Moreover, hematoxylin and eosin staining showed a reduction in the tumor mass in the lungs of LDI-treated mice with significant suppression of fibronectin and vimentin expression." (PMID 32365904, 2020). "The results showed that, compared with the control group, CD24, CD44, N-Cadherin, β-catenin, and Vimentin in tumor tissues before NAC were significantly overexpressed, and CD24, CD44, E-cadherin, N-cadherin, β-catenin, and Vimentin were significantly lower expressed in paracancer tissues before NAC." (PMID 33282946, 2020). "Therefore, an in-depth analysis of the biological functions mediated by vimentin and MRP1 can benefit for the precise development of UPS-targeted anti-tumor drugs." (PMID 32140187, 2020). "CNGs associated with poor outcome harboured transcription factors GATA3, GATA5, MLLT10, and TAF3 frequently amplified in HBCs15,19,28,41–43, EMT markers VIM, LAMA5, and ZEB121, and several genes enriching biological processes enhancing tumour-cell migration and motility." (PMID 31969654, 2020). "Furthermore, in NSCLC tumor tissues and cell lines (A549 and H1299), MALAT1 can upregulate VIM and downregulate CDH1 and is involved in the phosphorylation of AKT1, RPS6KB1, and MTOR." (PMID 32438606, 2020). "Moreover, immunohistochemical staining revealed that tumor cells were positive for CD31 and vimentin." (PMID 34567196, 2020).
tumor (continued). "On immunostaining, the tumor was positive for vimentin, CD34, and Bcl-2, and negative for α-smooth muscle actin (α-SMA)." (PMID 31848901, 2020). "Furthermore, the tumor cell invasion is facilitated by the activation of the Src/slug signaling that induces the expression of MMP-9/-2 and vimentin during the EMT." (PMID 32466169, 2020). "The tumor cells were immunoreactive for vimentin, smooth muscle actin, and desmin and negative for S100." (PMID 32992611, 2020). "The expression of vimentin in 231 cases of mRCC had no significant relation with sex, age, and initial tumor–nodes–metastases stage." (PMID 32850341, 2020). "For vimentin, a low proportion of positively stained tumor cells (<5%), and a negative or low staining score was observed in the majority of the cases." (PMID 32731632, 2020). "Furthermore, Vimentin and N‐cadherin, which function as EMT markers, were regulated by the α5‐nAChR/Stat3/Jab1 axis and contributed to tumour invasion and migration." (PMID 31930655, 2020). "In Slug-positive tumors, 4.0 ± 2.6% of tumor cells were cytokeratin/vimentin double positive compared to 1.9 ± 1.8% in Slug negative tumors (p = 0.001)." (PMID 32630033, 2020). "Of note, in this analysis there was no significant change in vimentin, possibly reflecting its expression in stromal cells in the tumor microenvironment." (PMID 32796899, 2020). "Vimentin, nestin, which are present in radial glia were also expressed in tumours, whereas neuronal marker NeuN was consistently absent." (PMID 32404936, 2020). "Additionally, this upregulation of VIM in MIA PaCa-2 was also significant compared to H treatment group, confirming that there exist specific contributions to invasive tumor cell phenotypes that derive from hypoxic stellate cells." (PMID 33105540, 2020). "This is further supported by immunofluorescence staining of the cell cultures with cytokeratin, that is negative in all and vimentin, that is positive in all WT cultures in all cells, i.e., these are homogeneous cultures of tumor cells." (PMID 33379206, 2020). "Notably, IHC of primary tumor samples was used to detect the alterations of BRD7, YB1, Ki67, E-cadherin and vimentin." (PMID 32028981, 2020). "POSTN expression in tumour stromal cells (i.e., CAFs) was evidenced on serial sections of tissues by the positive IHC reaction for α-smooth muscle actin (α-SMA), podoplanin (D2–40), and vimentin, which are characteristic markers of CAFs." (PMID 32987711, 2020). "Consistently, tumor cells in the xenografts formed by VAL-overexpressing LAD cells pre-silenced for Vimentin hardly generated invasive front or invaded into the neighboring subcutaneous tissue; meanwhile, silencing Vimentin did not affect tumor growth." (PMID 33046716, 2020). "On IHC, the tumour cells were positive for cytokeratin, EMA, and vimentin." (PMID 33520482, 2020). "Immunohistochemistry revealed increased staining for E-cadherin and vimentin in rat tumor tissues as compared to that in the matched normal tissues, suggesting that upregulation of SNHG17 stimulated EMT in HCC." (PMID 33519911, 2020). "Nevertheless, similar IHC expression of E-cadherin, N-cadherin, twist, and vimentin between margin and center of primary tumor has been reported, which suggests that no change in our results would be obtained from analysis of whole-tissue sections." (PMID 32300922, 2020). "Then β-catenin enters into the nucleus of tumor cells and upregulates the downstream markers such as CD44, TCF1/TCF7, and C-Jun to drive tumor carcinogenesis or EMT related genes such as N-cadherin, Vimentin, and Slug to mediate EMT process." (PMID 33505307, 2020). "In conclusion, in this pilot study, we have shown that measurement of EMT markers (E-cadherin, vimentin, claudin-1, and ZEB1) as well tumor-suppressive miR-205 allows for robust retrospective discrimination of localized ESD-resected and regional surgically resected samples." (PMID 32093260, 2020).
tumor (continued). "The tumor usually stains positive with antibodies to GFAP, S-100 protein, and vimentin." (PMID 32212579, 2020). "IHC staining of tumor tissues showed that protein levels of Ki-67 (a cell proliferation marker), CD31 (an angiogenic marker), N-cadherin and vimentin (two mesenchymal markers) were increased and E-cadherin (an epithelial marker) was decreased in A375CA-TLR4 tumors compared to A375NC tumors." (PMID 32312954, 2020). "In addition to cytoplasmic desmin/vimentin, few cells from 6 CAF primary cultures also expressed cytokeratin (6/15) presenting EMT of tumor cells." (PMID 32388727, 2020). "Given that OVOL1/2 inhibited the expression of EMT-related factors such as vimentin and ZEB1, we hypothesized that knockdown of OVOL1 or OVOL2 may enhance tumor cell invasion." (PMID 32106476, 2020). "The anti-pan cytokeratin antibody cocktail and the anti-vimentin antibody strongly stained human tumor cells; 4T1 mouse tumor cells showed minimal or absent staining with the same set of antibodies." (PMID 31462307, 2019). "Furthermore, H&E and IHC analyses revealed that the invasive border of the tumor and the expression of NKCC1, vimentin, and MMP2 were decreased in the U87‐Sh groups, which is consistent with the in vitro results." (PMID 30159893, 2019). "Tumors expressing E-cadherin (p=0.001) did not express vimentin orTWIST (p=0.020), and E-cadherin expression was low in patients with portalthrombosis per tumor (p=0.007), demonstrating the importance of EMT in spreadingtumor cells from the primary tumor." (PMID 31038558, 2019). "Immunostaining of tumour cells with CD117 (Dako, 1:500 dilution), S-100 (Dako, 1:400 dilution), CK-WSS (Dako, 1:500 dilution), CK AE1-AE3 (Dako, 1:200 dilution), Vimentin (Dako, 1:100 dilution) and Chromogranin (Dako, 1:1000 dilution) antibodies did not yield any positive reaction." (PMID 31038324, 2019). "While the expression of vimentin in ESCC tumour tissues was 47% (47/100), and none of the normal tissues expressed vimentin in CAN tissues (0%)." (PMID 31186031, 2019). "To investigate whether ALDH3A1 expression might be involved in mesenchymal phenotype development, we studied EMT markers (CDH1, Zeb1, VIM, and FN1) at the mRNA expression level in all stem-cell-like tumor cells." (PMID 31817719, 2019). "IHC analysis of the primary tumor tissues showed that estrogen promoted the expression of CD49f, ERα, NOTCH1, and Vimentin, and that the expression of E-cadherin was decreased; the changes induced by E2 were significantly inhibited by tamoxifen, and the Western blot results showed the same trends." (PMID 31122254, 2019). "On a similar note, markers such as vimentin are not specific to tumour cells as they are also expressed by other cell types in the tumour microenvironment, like, fibroblasts." (PMID 30194451, 2019). "Immunohistologic analysis demonstrated the tumor cells were positive for α-smooth muscle actin, β-catenin and Vimentin, and negative for AE1/AE3, Bcl-2, CD34, CD117, Factor VIIIR Ag, S-100 protein, or STAT6." (PMID 30206803, 2019). "In addition, the expression levels of PTEN, vimentin, and vascular endothelial growth factor-a (VEGFA) have been determined with the aim of obtaining further information regarding the tumor cells’ aggressiveness." (PMID 31453379, 2019). "For example, a transgenic mouse model of lung cancer with KrasG12D, Lkb1fl/fl showed that although primary tumor growth was unaffected, metastasis was inhibited by the absence of vimentin." (PMID 31126068, 2019). "Additionally, overexpression of circGRAMD1B triggered a reduction of Ki-67, PCNA, and Vimentin expression, while an increase of circGRAMD1B, PTEN, p21, and E-cadherin mRNA level in excised tumor masses." (PMID 31719211, 2019). "The tumour cells were positive to vimentin and CD68, and negative to desmin, SMA, S100 protein, EMA, cytokeratins AE1/AE3, CD117, and CD34 antibodies." (PMID 31773099, 2019).
tumor (continued). "In the mouse tumour tissues, IHC analysis revealed that increased expression of SNAIL, VE‐cadherin and vimentin was observed in the HepG2‐LOXL2 cell‐xenograft tumours compared with the HepG2‐control cell‐xenograft tumours, whereas LLGL2 and E‐cadherin were expressed at lower levels." (PMID 30506621, 2019). "However, in the tumor of mice after AOM/DSS treatment, we observed a slight increase in the staining of vimentin within the epithelial section, which suggests a change in the characteristics of these cells from epithelial toward mesenchymal phenotype." (PMID 32566755, 2019). "Immunohistochemical staining was performed in six PSPs, and we found that some tumor cells were immunopositive for epithelial membrane antigen (EMA) (3/6), thyroid transcription factor‐1 (TTF‐1) (6/6), vimentin (2/6), CD68 (2/6) and cytoskeleton 7 (CK‐7) (4/6)." (PMID 31131992, 2019). "Vimentin is considered a cancer marker as it is overexpressed in most epithelial cancers undergoing epithelial to mesenchymal transition (EMT), and its overexpression correlates well with accelerated tumour growth, invasion, angiogenesis and poor prognosis." (PMID 30894168, 2019). "Immunohistochemical analysis showed that the tumour was positive for vimentin, CD99, Bcl-2 and CD34 and negative for D2–40, desmin, S-100, SMA and CK and the Ki-67 index was as low as 1%." (PMID 31391089, 2019). "CK immunostaining was applied to confirm the immunoreactivity of the tumor tissue, whereas immunostaining for SMA, vimentin, or calponin was used to examine whether the epithelial tumor tissue contained an immunoreactivity for these markers." (PMID 31569405, 2019). "We found that hRAT-CMs increase the expression of vimentin in a non-tumor cell line, which indicates that factors present in the CMs from hRAT have the ability to revert the phenotype of non-tumor epithelial cells to a mesenchymal phenotype." (PMID 31534630, 2019). "In this regard, the slightly higher median values for calponin in comparison to the comparable median values for SMA and vimentin were likely related to the calponin expression in some tumor cells and ME cells, whereas SMA and vimentin were restricted to ME cells." (PMID 31569405, 2019). "Other antigens commonly used for tumor characterization were S‐100, desmin, vimentin, actin, smooth muscle actin, cytokeratin, and DOG1 (data not shown)." (PMID 31397088, 2019). "Besides, high expression levels of vimentin, another EMT marker, and vascular endothelial cadherin (VE-cadherin), a tumor angiogenic and progression marker, have been shown at invasive front in OSCC and MEC." (PMID 31579438, 2019). "Thus, E-cadherin, N-cadherin, vimentin, MMP2 and MMP9 were identified as attractive cancer targets that all play important roles in the context of tumour metastasis." (PMID 31423109, 2019). "Immunocytochemical analysis showed that tumor liver MSCs and non-tumor liver MSCs are also positive for vimentin, α-SMA, and N-cadherin, and negative for epithelial markers cytokeratin 18 and E-cadherin." (PMID 31546729, 2019). "Pan-cytokeratin x100 did not indicate anyreactivity in the tumor cells,and non-reactive tumor cells were indicated by vimentin." (PMID 30892391, 2019). "These biomarkers include ADAM17, MMP2, MMP9, and MMP11, survivin and CK19, vimentin, CXCR4, ING5, and Stanniocalcin2; in all of these examples, these molecules are overexpressed in tumoral GC tissues." (PMID 31249523, 2019). "These regions were smaller and less prominent than in GS tumours, and also showed heterogeneous expression of GFAP, vimentin, EphA2, EphA3 αDG, CD49f and CD31, indicating that this tumour tissue patterning might also occur in GBM (Online Resource 2b)." (PMID 31463571, 2019). "Moreover, IHC analysis of tumour tissues from the KPC mice, showed a clear reduction in surrounding stroma, demonstrated by decreased vimentin levels in tissues from MCI-715-treated mice." (PMID 31378204, 2019).